BCL6 (BCL6 transcription repressor)
Diseases named in the same sentence as BCL6 in open-access papers (continued):
Sharing a sentence is not in itself a finding about the gene and the disease.
infection (79 papers, 2010 to 2025). The state of being infected such as from the introduction of a foreign agent such as serum, vaccine, antigenic substance or organism. "CD40L blockade and Bcl6+CD4+ T cell deficiency both dampen TFH responses yet have opposing effects on control of infection." (PMID 37721965, 2023). "We found that Tcf7, which encodes Tcf1 and is involved in early induction of Bcl6, was downregulated under HIVYu2b infection in all CD4+ T cell transitions toward the TfhD3 profile." (PMID 34984326, 2022). "We also observed a significant reduction in both the level of Bcl-6 protein expression and frequency of NP-specific Bcl-6+ cells in Aiolos-deficient CD4+ T cells at an early timepoint post-infection, supporting a role for Aiolos in the positive regulation of Bcl6 expression in vivo." (PMID 36964178, 2023). "Concurrently, Bcl-6 protein level was remarkably lower in Uba3-deficient CD4+ T cells than in Uba3-sufficient counterparts at day 7 of infection, and the proportion of IL-21-producing CD4+ T cells in the spleen was also found to be lower in Uba3ΔT mice at this time." (PMID 30462731, 2018). "Runx1 overexpressing SMARTA cells (OE) produced fewer Tcf1+ CXCR5+ and Bcl6+ Tfh cells by percent at 3.5 days post infection." (PMID 39677644, 2025). "Approximately 15–20% of B cells in the dLNs of rLCMV-infected mice expressed high levels of T-bet seven days post-infection, compared to a meager 1% expressing Bcl-6." (PMID 40169810, 2025). "Analysis of experimental infection cases demonstrated that cats with high anti-SFTSV antibody titres contained high numbers of Bcl6-positive cells in their germinal centres." (PMID 38249467, 2023). "Although multiple lines of evidence show that Bcl6 and Tbet cross inhibit each other, infection-induced Tfh cells can transiently express Tbet and Th1 features." (PMID 37275873, 2023). "We found that levels of TBX2, GATA3, RORC, SPI1, and BCL6 in the livers of infected rabbits were elevated on days 5 and 15 post-infection (PI)." (PMID 37593762, 2023). "For example, the expression of many TFs changed significantly over the course of infection, including decreases in Fos, Jun, and BCL6, and increases in Bach2 and BATF." (PMID 33497421, 2021). "Both Th1-like IFN-γ+IL-21- and hybrid IFN-γ+IL-21+ Teff were significantly increased in the short-term infection in Bcl6 TKO mice compared with WT, showing a larger effect of Bcl6 on IFN-γ expression in shorter stimulation than longer." (PMID 32634740, 2020). "Mechanistically, T-bet, and not STAT1 or STAT4, regulated IFN-γ production by T cells; and T cell-intrinsic expression of STAT3, Bcl6, and Blimp-1 each regulated T-bet expression during the peak of infection." (PMID 32634740, 2020). "Using flow cytometry, we measured GC B cell numbers and the expression of CXCR5, PD-1, IFN-γ, IL-21, T-bet, and Bcl6 in Teff for the first 30 days of infection." (PMID 32634740, 2020). "Several studies have demonstrated that STAT3 was indispensable for Tfh and Tfr cell differentiation by inducing the expression of Bcl-6 during immunization or infection." (PMID 31382877, 2019). "Under conditions of infection by different types of pathogens, many shared transcription factors (TFs), such as Bcl-6, TCF-1, and Maf, are selectively enriched in pathogen-specific TFH cells, orchestrating TFH cell differentiation and function." (PMID 30984183, 2019). "Ki67 and BCL6 expression in spleen and lungs of mice at d35 post-infection was visualized by confocal microscopy." (PMID 30984186, 2019). "Administration of an IL-6-neutralizing Ab or IL-6R-blocking Ab 20 days after infection reduces Bcl6 expression, TFH and GC B cells." (PMID 30405612, 2018). "Knockdown of STAT1 in mouse T cells results in defective generation of early CXCR5+Bcl6+ TFH cells 2 days after infection." (PMID 30405612, 2018).
infection (continued). "In search for the underlying mechanisms, we demonstrate reduced Bcl-6 accompanied by accumulated FoxO1 proteins in CD4+ T cells of Uba3ΔT mice, either under the circumstance of P. yoelii 17XNL infection or the iTfh cultures." (PMID 30462731, 2018). "The infected cells were harvested at different time points (0, 2, 4, 7 and 15 days post-infection), then mRNA was extracted and Real-time PCR was performed for Bcl6 detection." (PMID 28738086, 2017). "When the disease progressed from the chronic to the advanced stage, the expression level of Bcl-6 still kept relatively higher level compared to that of before infection." (PMID 29192177, 2017). "Bcl6 was downregulated at 3 dpi, but was upregulated in 42 dpi, suggesting that F. gigantica infection can modulate Bcl6 expression (a traditional regulator of a Th2 response) over the course of infection." (PMID 28143561, 2017). "Blocking DENV RNA replication and infection of DCs with DENV RNA replication inhibitor SDM25N abolished the formation of IL-21-secreting CXCR5+PD-1+Bcl-6+ TFH cells." (PMID 29186193, 2017). "Consistent with enhanced humoral immunity, we found α-IFNAR treatment resulted in 2 to 3-fold expansions in the frequency and total number of Plasmodium-infection-induced splenic PD-1+CXCR5+Bcl-6+ Tfh cells." (PMID 27732671, 2016). "On the other hand, genes linked to cell proliferation and apoptosis (e.g., BCL6, APOE, PDCD4, and RARES2) emerged as the top inhibited master molecules due to infection." (PMID 26865111, 2016). "Tfh isolated from the mediastinal LN 9 days after infection exhibited heightened Bcl6 expression along with decreased CCR7 (e respectively) relative to the NonTfh population." (PMID 27329272, 2016). "Taken together, these findings suggest one or more Bcl6 expressing CD4+ T cell populations may be necessary for efficient control of infection, or that outgrowth of TReg in CD4CreBcl6fl/fl mice drives enhanced susceptibility to challenge." (PMID 37721965, 2023). "Moreover, induced ablation of Bcl6 converts “ex-TFH” cells into TH1 cells during acute lymphocytic choriomeningitis virus (LCMV-Armstrong) infection, suggesting that Bcl6 is critical for the integrity of TFH cells." (PMID 36045674, 2022). "Moreover, Th2 response and Bcl6 expression in CD4+ T cells were also increased in vivo by blocking PD-L1 after infection, although the hepatic pathology was slightly influenced." (PMID 32197642, 2020). "As expected, a substantial proportion of TFH cells (ICOS+Bcl6+) formed by 7.5 days post infection (~30% of CD4+ T cells) while only few follicular regulatory T cells (TFR, Foxp3+Bcl6+) were generated by this time point, representing ~7% of Foxp3+ T cells and ~0.5-1% of all CD4+ T cells." (PMID 33519801, 2020). "Bcl6 expression increased in Tfh-like and GC Tfh cells from WT and Icos-/- mice after re-infection." (PMID 32348365, 2020). "Macaque Tfh normally express very little CCR5, yet are infected by CCR5-using SIV, which may occur mainly through infection of a subset of PD-1intermediateCCR5+Bcl-6+ pre-Tfh cells." (PMID 28553284, 2017). "We therefore explored the effects of inactivation of the Bcl6 gene in T cells [Bcl6fl/flCD4-cre+/−] or the Sh2d1a gene [Sh2d1a−/−, encoding SAP] on the ability to control a chronic P. chabaudi blood-stage infection." (PMID 28888925, 2017). "In human studies, circulating Tfh cells, a subset of CXCR5+Bcl6+ CD4+ T cells in the blood, serve as biomarkers for immune responses, including vaccine efficacy, autoimmunity, and infections." (PMID 40634636, 2025). "BCL6 mRNA and IL21 were increased with the infection (p < 0.01 and p < 0.05, respectively) on day 5 PI." (PMID 37593762, 2023). "Deletion of Bcl6 in CD4+ T cells and CD40L blockade both thwart development of GC responses in Brucella infected mice yet have opposing effects on control of infection." (PMID 37721965, 2023).
infection (continued). "Initially, the expression of Blimp1, T-bet and Bcl6 transcriptional factors was evaluated in CD4+ T cells from B6 and P2rx7-/- mice at the acute phase of infection." (PMID 36993971, 2023). "In an acute infection model, ICOS is required for the early CXCR5+Bcl6+ TFH differentiation of antigen-specific T cells as early as 3 days following infection with lymphocytic choriomeningitis virus (LCMV)." (PMID 30405612, 2018). "The expression of CD8a, CD74, and BCL6, which are regulators of MHC class II molecules and B-cell differentiation, was downregulated during early vvIBDV infection." (PMID 28086922, 2017). "Notably, 12 of these TFs exhibited distinct phosphorylation patterns upon infection, including MED14, SIN3A, BCL6, cJUN, NFATC1, STAT3, RUNX3, GTF2F1, MED1, JUNB, TLE3, and FOSL2." (PMID 40368139, 2025). "Th2 response genes such as Il13ra2, Il4ra and Bcl6 are upregulated in the NPH, suggesting these are crucial genes to fight off infection by induction of parasite-specific IgG and IgE, smooth-muscle cell contractility, intestinal permeability and resistin-like molecule (RELM)-beta secretion." (PMID 36883013, 2023). "For example, GIMAP7 was consistently down- and BCL6 transcription repressor (BCL6) upregulated from 4 h to 7 days post-infection (and the present study), regardless of the cellular proliferative response to the TCR stimulus." (PMID 37111397, 2023). "In Bcl6 TKO animals, T-bet expression was maintained at intermediate levels in Teff from day 7 to day 9 p.i., suggesting Bcl6 controls T-bet expression at the peak of infection." (PMID 32634740, 2020). "Strikingly, DENV-infection of DCs induced a robust CXCR5+PD-1+ subset of differentiated TH cells, which expressed high levels of TFH-specific transcription factor Bcl-6." (PMID 29186193, 2017). "Following Lm‐2W1S infection, three subsets of CD4+ T cells can be defined: CXCR5−PD‐1−T‐bet+ effector cells (Teff) that give rise to Tem cells, CXCR5+PD‐1−Bcl‐6+ central memory precursors that give rise to Tcm cells and CXCR5+PD‐1+Bcl‐6+ Tfh cells." (PMID 25754933, 2015). "While IL-21 and CXCR5, widely considered Tfh-related molecules, are both predominantly expressed by IFN-γ+ cells in this infection, this population is not regulated by Bcl6." (PMID 26646149, 2015). "However, 12 days post infection, Cd28flox/floxOx40cre/+ mice had reduced numbers of CXCR5+Bcl-6+CD4+ Tfh cells and IFNγ+CD44highCD4+ Th1 cells in the medLN and Th1 cells in the lungs compared to control mice." (PMID 25347065, 2014). "Likewise, Notch2-dependent cDC2 in the intestinal lamina propria (LP) are reduced in the absence of Bcl6 in DC, leading to a decrease in T helper 17 cell (Th17)-responses and delayed healing upon infection with the enteric pathogen Citrobacter rodentium." (PMID 38688934, 2024). "Concurrent with this, the peaked Bcl6 expression did not occur till 2-3 h post infection." (PMID 26728228, 2016). "Furthermore, B cell-deficient μMT mice infected with LCMV were shown to have no defect in CD4+ T cell expression of Bcl6 or CXCR5 at day 3 post-infection, suggesting that B cells are not exclusively responsible for promoting early Tfh cell induction." (PMID 27559335, 2016). "Following Lm-2W infection, three subsets of 2W1S-specific CD4+ T cells have been elegantly described 19: CXCR5−PD-1−T-bet+ effector T cells (where PD-1 is programmed death-1), CXCR5+PD-1−Bcl-6+ cells that give rise to central memory cells and CXCR5+PD-1+Bcl-6+ TFH cells." (PMID 24771127, 2014). "Altogether, our study first reveals that the transcription factor BCL6 specifically drives the differentiation of PD-1+CD8+ TSCM-like regulatory cells in donor G-PBSC, which may serve as an important cellular immune mechanism for the balance of aGVHD, anti-infection and GVL activities in recipients." (PMID 40175340, 2025).
infection (continued). "A recent study in mice reported that memory TFH cells have reduced mRNA expression of TFH markers such as Bcl6, IL-21, ICOS and PD-1 compared to the effector TFH population, indicating the expression of these molecules may change depending on the phase of infection." (PMID 24497824, 2014). "FX1 is the first reported Bcl6 inhibitor endowed with higher affinity for the Bcl6 BTB domain than the endogenous corepressors and exhibited a favorable pharmacokinetic in vivo and lack of toxicity, inflammation, or infection." (PMID 40290124, 2025). "Prior to day 6 post-infection, for example, Icos−/− CD4+ T cells were not defective in their ability to express the canonical Tfh cell markers Bcl6, PD-1, CXCR5, or IL-21." (PMID 27559335, 2016). "To address whether our results were due to a lack of Bcl6 in bona fide DCs, we infected Clec9a.Bcl6KO mice and controls with C. rodentium and analyzed their CD4 T cell compartment on day 9 post-infection." (PMID 38688934, 2024). "Similarly, we found no upregulation of Bcl6, PRDM1, and ZBTB7B (Thpok) in memPD-1neg-derived TfhD3 cells under HIVYu2b infection." (PMID 34984326, 2022). "Flow cytometry analysis revealed that, although conventional CD4+ T cells gradually express CXCR5, PD-1, Bcl6, and SLAM and produce high levels of IL-21 after infection, TCRβ+CD1d-tetramer+ NKT cells do not upregulate Bcl6, CXCR5, or PD-1 and express moderate levels of SLAM and IL-21." (PMID 29249358, 2018). "Notably, although NcoR2 and HDAC3 remained at a high level over the infection period, they failed to reside on IRF7 promoter and hinder its transcription when Bcl6 expression was suppressed by miR-127." (PMID 26728228, 2016). "The expression of BACH2 and BCL6 was not changed or was only marginally affected in SKW6.4 cells transduced with lentiviral vectors expressing miR-34a-5p, -148a-3p, or -183-5p at a low multiplicity of infection (moi)." (PMID 26655851, 2015). "The upregulation of Bcl6 in non-permissive mice suggests that the ASPs may only be able to successfully inhibit B-cell signalling in PHs, while the NPH can upregulate its B-cell response following infection." (PMID 36883013, 2023).
hematologic malignancies (6 papers, 2010 to 2026). "These include targeting the direct oncogenic role played by BCL6 in hematological malignancies." (PMID 39456751, 2024). "BCL6 has additionally been identified as a driver of other hematological malignancies." (PMID 39456751, 2024). "It has also been suggested that lncRNAs may play a role in the chromosome breaks involved in typical gene rearrangements in hematologic malignancies, such as BCL-6 translocation." (PMID 33593440, 2021).
bacterial infection (3 papers, 2014 to 2022). "We have demonstrated that rifamycin SV and rifabutin, members of the ansamycin antibiotic family, that have clinical uses in the prevention or treatment of bacterial infections due to binding and inhibition of bacterial DNA-dependent RNA polymerase, are able to bind the BCL6-POZ domain." (PMID 24595451, 2014). "Recently, the relationship between host defense in bacterial infection and liver lipid metabolism has been elucidated, and while Bcl6 has a negative effect on liver lipid accumulation and abnormal glucose tolerance, it is important for the defense against bacterial infection." (PMID 36497010, 2022).
blood cancers (3 papers, 2023 to 2025). "BCL6, a transcriptional repressor linked to blood cancers and solid tumors, suppresses tumor suppressor genes while promoting those involved in cell proliferation and immune evasion, contributing to chemotherapy resistance." (PMID 39796244, 2025). "Highly analogous behaviour is exhibited by ZBTB family members BCL6 (aka ZBTB27) and the Drosophila Abrupt protein (probably ZBTB14) in blood cancers." (PMID 40460875, 2025).
cardiovascular disease (3 papers, 2022 to 2025). "Additionally, some of the predicted genes, including BCL6, LDB3, MUC1 and SYNC, have been implicated in other cardiovascular diseases." (PMID 38100461, 2023). "All of these data suggest the importance of BCL6 in cardiovascular disease or senescence." (PMID 36582740, 2022).
inflammation (3 papers, 2016 to 2023). Aberrant reaction of the microcirculation characterized by movement of fluid and leukocytes from the blood into extravascular tissues. "Of note, Bcl6-deficient ST2+ Tregs promote airway inflammation in the context of house dust mite-induced allergic airway inflammation, indicating that Bcl6 is necessary for the suppressive function of ST2+ Tregs." (PMID 37197653, 2023). "A more recent study reported that RARα signaling enhances Tfh differentiation in an airway inflammation mouse model, perhaps through inhibiting IL2Rα upregulation on T cells, as IL2R signaling inhibits Tfh differentiation by repressing BCL6." (PMID 35359939, 2022).
neurodegenerative disease (3 papers, 2014 to 2022). A disorder of the central nervous system characterized by gradual and progressive loss of neural tissue and neurologic function. "Of the transcription factors altered in female PD patients, ATF3, BCL6, and PCGF2 have been previously associated with neurodegenerative diseases or cognitive disabilities." (PMID 36414996, 2022). "Specific TFs activated with an NES > 0 (female PD patients), such as ATF3, BCL6, or PCGF2, have been associated with neurodegenerative diseases or cognitive disabilities." (PMID 36414996, 2022). "The BCL6 transcriptional repressor targets the ITM2B gene, which has important links to neurodegenerative diseases such as AD." (PMID 36414996, 2022).
immune diseases (2 papers, 2021 to 2023). "Metabolic reprogramming of B cells has been shown to integrate epigenetic activation of BCL6 gene to induce germinal center B cell differentiation, thus confirming its crucial pathogenic role in lymphomagenesis and immune diseases." (PMID 37835497, 2023).
metabolic disease (1 paper, 2022). A congenital disorder (due to inherited enzyme abnormality) or acquired (due to failure of a metabolically important organ) disorder resulting from an abnormal metabolic process. "Drugs which enhance BCL6 expression or modify the transcriptional regulation of BCL6 and CD36 represent an effective treatment method for NAFLD and associated metabolic diseases." (PMID 35436984, 2022).
BCL6 also shares sentences with these, for which no sentence is quoted: mantle cell lymphoma (14 papers); central nervous system lymphoma (7); Hodgkins lymphoma (5); multiple myeloma (4); cervical carcinoma (3); sarcoma (3); acute leukemia (2); acute monocyte leukemia (2); adenocarcinoma (2); atrial fibrillation (2); breast (2); colon adenocarcinoma (2); cutaneous melanoma (2); lymphopenia (2); Parkinson disease (2); Sjögren's syndrome (2); small cell lung carcinoma (2); Stroke (2); Abdominal obesity (1); aggressive (1); alcoholic liver diseases (1); allergic asthma (1); allergic rhinitis (1); angiosarcoma (1); ataxia telangiectasia (1); autoimmune thyroiditis (1); B-cell acute lymphoblastic leukaemia (1); bladder tumors (1); breast adenocarcinoma (1); breast benign disease (1).
A further 85 diseases each share a sentence with BCL6 in 1 paper.